RNU7-35P (RNA, U7 small nuclear 35 pseudogene)
Synonyms: U7.35
Gene: Small nuclear RNA gene on chromosome 7 (43,194,421 to 43,194,482, forward strand). Ensembl gene ENSG00000252983.
Homologues: Orthologues: chimpanzee U7 (95% identical), macaque U7 (89% identical), pig U7 (85% identical). Paralogues in human: RNU7-143P (90% identical), RNU7-52P (90% identical), RNU7-7P (90% identical), U7 (90% identical), RNU7-12P (89% identical), RNU7-23P (89% identical), RNU7-28P (89% identical), RNU7-60P (89% identical), RNU7-67P (89% identical), RNU7-6P (89% identical), RNU7-167P (87% identical), RNU7-18P (87% identical), and 142 more.